INS (insulin)
Diseases named in the same sentence as INS in open-access papers (continued):
Sharing a sentence is not in itself a finding about the gene and the disease.
Insulin resistance (continued). "We hypothesized that high muscle (HM) cows would have increased insulin resistance, as indicated by elevated insulin concentrations with no change to glucose." (PMID 39877192, 2025). "These distinctions capture variation in insulin production and secretion capacity, which is central to the development of T2D in individuals whose beta cells fail to maintain glycaemic control, even in the absence of pronounced insulin resistance." (PMID 40741412, 2025). "Furthermore, resting HR showed a positive correlation with insulin, but negative correlations with QUICKI, HDL-C, and BUN, reflecting that adiposity, blood pressure, insulin resistance, dyslipidemia, kidney function, and HRV were associated with MetS." (PMID 41162612, 2025). "In order to assess the issue of subcutaneous insulin resistance, several serological tests for autoimmune markers were performed, with negative results, except for a mild and fluctuating positivity for anti-insulin antibodies in a patient not insulin naïve." (PMID 40995084, 2025). "On the other hand, PCOS reproductive types of patients can either present with key metabolic disturbances or may have normal insulin levels and no clinically relevant insulin resistance, as well as decreased HDL cholesterol levels (mostly A and B phenotypes)." (PMID 40869469, 2025). "While dietary AGEs in male correlated with fasting triglycerides (p = 0.034) but not with insulin resistance, in females the intake of AGEs correlated positively with fasting blood insulin (p = 0.034) and HOMA-IR (p = 0.022) and negatively with total (p = 0.005) and LDL-cholesterol (p = 0.002)." (PMID 40263184, 2025). "Furthermore, insulin-specific CD8 T cells from high-H exhibited increased expression of the activation markers CD69 and LAG3 compared to bulk CD8 T cells, but not to low-H individuals, suggesting that their activation is independent from insulin resistance." (PMID 39656436, 2025). "Furthermore, the use of insulin sensitizers and insulin secretagogues may interfere with HOMA-IR, HOMA-β, and QUICKI measurements, potentially affecting the accurate assessment of true insulin resistance in patients." (PMID 41585795, 2025). "Our findings suggest that in adults with type 1 diabetes, metformin may have metabolic impacts that translate to sparing of insulin requirements via effects independent of insulin resistance." (PMID 41285865, 2025). "Consequently, it can also be inferred that PSPW may curb gluconeogenesis and enhance glycogen synthesis by activating the insulin-mediated PI3K-AKT-FoxO1/GSK3 signaling pathway, thereby ameliorating insulin resistance and hyperglycemia." (PMID 41001671, 2025). "Reduced of fasting blood glucose (FPG), insulin, insulin resistance (IR) and glycosylated hemoglobin in propolis groups.Exercise with propolis consumption compared with exercise and propolis had a more significant effect on lowering FBG, insulin, IR, and glycosylated hemoglobin." (PMID 40078415, 2025). "Additionally, despite not being based on plasma insulin levels, it demonstrated a significant and positive correlation with indices of insulin resistance and beta-cell dysfunction." (PMID 40218212, 2025). "No abnormalities in fasting insulin and insulin resistance index were found in either group." (PMID 41323197, 2025). "Although myricitrin did not affect fasting blood glucose levels, it lowered plasma insulin, hemoglobin A1c, postprandial glucose levels, and the homeostasis model assessment of insulin resistance, suggesting improvements in insulin sensitivity and glucose homeostasis." (PMID 40286055, 2025). "The aim of this study was to determine whether maternal GDM in absence of maternal obesity and insulin resistance affects offspring glucose homeostasis and tissue-specific insulin sensitivity." (PMID 40021748, 2025).
Insulin resistance (continued). "In this study, insulin, Homeostatic Model Assessment for Insulin Resistance (HOMA-IR), and other indices of insulin resistance were not measured, which limits the ability to corroborate CA’s potential effects on pathways influencing β-cell function and insulin resistance." (PMID 41383475, 2025). "However, due to the lifelong subcutaneous insulin injections required in T1DM, relative peripheral hyperinsulinemia and hepatic hypoinsulinemia may occur, leading to insulin resistance." (PMID 38681765, 2024). "However, shortly after its clinical application, it was observed that exogenous insulin did not uniformly lower glucose levels in all diabetic patients, leading to the introduction of the concept of insulin resistance (IR) to the scientific community." (PMID 39337290, 2024). "Consequently, researchers developed the homeostasis model assessment of insulin resistance (HOMA-IR) for clinical studies; however, this model is susceptible to exogenous insulin therapy and is not suitable for patients with β-cell incompetence." (PMID 38773587, 2024). "Taking into consideration this dynamic nature of the degree of insulin resistance, a history of T2DM may be viewed as a proxy for a temporary exposure to increased insulin and IGF levels and thus promotion of cell growth, which could increase the risk of cancer." (PMID 38492115, 2024). "However, male LivARKO-HFD mice displayed lowered insulin stimulated p-AKT in the liver compared to mice not given insulin (green unfilled compared to green filled bars), suggesting that these mice are experiencing hepatic insulin resistance." (PMID 38425436, 2024). "Insulin resistance (IR) refers to the reduced sensitivity and reactivity of insulin target organs (liver, adipose tissue and skeletal muscle) to endogenous or exogenous insulin, resulting in lower glucose uptake and utilization than normal." (PMID 39290619, 2024). "This can occur from a resultant overdose of exogenous insulin since loss of pancreatic β-cells (type 1 diabetes) or pancreatic insulin insufficiency and insulin resistance (late-stage type 2 diabetes) do not sufficiently correct hypoglycaemic states following the administration of exogenous insulin." (PMID 38392992, 2024). "This indicates that the insulin requirements of individuals with gestational diabetes mellitus (GDM) may surpass the functional capacity of pancreatic β-cells, a phenomenon influenced by the degree of insulin resistance." (PMID 39876919, 2024). "A lack of insulin or insulin resistance, and consequently hyperglycemia, leads to many systemic disorders, among which diabetic encephalopathy (DE) is a long-term complication of the central nervous system (CNS), characterized by cognitive impairment and motor dysfunctions." (PMID 39062768, 2024). "Moreover, the fasting serum insulin level was increased after chemerin treatment or Ucp1 gene ablation, even though the homeostasis model assessment of insulin resistance (HOMA-IR) showed a modest increase without a statistical difference." (PMID 38933207, 2024). "The primary aim of this study was to evaluate whether plasma concentrations of glucagon, total GLP-1, and total GIP during an OGTT differ between children and adolescents with obesity and insulin resistance (OIR), obesity and normal insulin sensitivity (OIS), and controls with NW." (PMID 38087928, 2024). "Additionally, insulin resistance has not been evaluated in our study because patients’ insulin values were not accessible." (PMID 38827857, 2024). "Altered glucose homeostasis, specifically insulin regulation, and impaired glucose tolerance, as well as derangements in lipid metabolism, are consistently reported in FEP populations, manifesting as hypertriglyceridemia, insulin resistance, and reduced total and LDL cholesterol levels." (PMID 38421095, 2024).
Insulin resistance (continued). "Insulin resistance is a condition in which the body does not respond effectively to insulin, leading to elevated insulin levels in the bloodstream and in turn, can result in various metabolic consequences, including difficulties in regulating blood sugar levels." (PMID 39054488, 2024). "Regarding insulin, the hormone responsible for mediating BGL balance within the body, the HFD-group mice had significantly higher serum insulin and fasting blood glucose levels than the STD group, with a significantly elevated homeostatic model assessment–insulin resistance (HOMA-IR) index." (PMID 39517172, 2024). "Zebrafish muscle insulin resistance model (zMIR): We have established a novel insulin-resistant zebrafish model (zMIR) that possesses a dominant-negative form of the IGF-1 receptor inhibiting both insulin and IGF signaling in fast twitch muscles." (PMID 38540087, 2024). "In another meta-analysis that compared insulin resistance markers in women with recurrent pregnancy losses with healthy women, women with recurrent pregnancy losses had significantly higher fasting plasma insulin, higher HOMA-IR, and lower glucose to insulin ratio." (PMID 39328462, 2024). "Similarly, we only assessed one indicator of insulin resistance (pAkt) following insulin stimulation; however, Akt is a target of insulin downstream of IRS1 and PI3K and is regarded as a central node in the proximal insulin signaling cascade." (PMID 39057712, 2024). "Based on our findings, we suggest that increased insulin signaling promotes the expression of CUL1, resulting in the breakdown of IRS1 to turn the signaling off temporarily; however, prolonged overnutrition disrupts IRS1 consistently, leading to the development of insulin resistance." (PMID 38212312, 2024). "In vitro, CK activates PINK1/Parkin-mediated mitophagy in insulin-resistant cellular models established by FA and HG-treated mouse adult myoblasts (C2C12), promotes mitochondrial fission/fusion stabilization, and ameliorates FA-induced insulin resistance in skeletal muscle cells." (PMID 38348222, 2024). "It was suggested that ectopic lipid accumulation stimulates insulin resistance and lipid metabolites, such as diacylglycerol, lipophosphatidic acid (LPA), ceramides and acylcarmitines, contributing to the development of insulin resistance in the liver and skeletal muscle." (PMID 38397072, 2024). "In terms of insulin resistance, IL-1β interferes with insulin signaling by activating stress kinases like JNK and inhibitor of nuclear factor kappa B kinase subunit beta (IKKβ), which phosphorylate insulin receptor substrate proteins and disrupt downstream insulin signaling cascades." (PMID 38044678, 2024). "However, since plasma magnesium is negatively correlated with insulin resistance, we expect no improvement in insulin sensitivity after magnesium supplementation in people with insulin-treated type 2 diabetes and a normal serum magnesium." (PMID 37922013, 2024). "Insulin and insulin resistance indices were not altered by BCA or BCK (P > 0.20)." (PMID 38281954, 2024). "However, that the analysis of mechanisms for correcting metabolic abnormalities using insulin resistance failed to evaluate some non-insulin-sensitive tissues." (PMID 39179999, 2024). "It was found that vitamin D supplementation did not improve insulin resistance or glycemic control but might increase insulin secretion." (PMID 39599690, 2024). "Furthermore, has a suppressive impact on protein phosphatase activity and participates in lipid metabolism and insulin resistance, however, in avian skeletal muscle insulin does not affect muscle glucose transport, mainly due to the lack of the SLC2A4 gene." (PMID 38717527, 2024). "Originally, MODY was defined by the following criteria: onset before 25–35 years of age, lack of insulin dependence (evident by C-peptide levels or type of treatment), lack of obesity, signs of insulin resistance, and autosomal dominant inheritance over multiple generations." (PMID 39408828, 2024).
Insulin resistance (continued). "In cells where ethanol was used as the solvent, we observed a slightly higher amount of mtDNA in control cells with induced insulin resistance (IR+ ethanol) compared to cells with normal insulin sensitivity (IR− ethanol); however, the increase was not statistically significant." (PMID 39339765, 2024). "Insulin resistance generally refers to a condition in which the body does not respond properly to insulin, affecting glucose transport and metabolism in adipocytes and skeletal muscle, as well as decreasing the ability to suppress glucose production in the liver." (PMID 38543073, 2024). "Children and adolescents with obesity and insulin resistance have elevated concentrations of fasting plasma glucagon and GLP-1, elevated glucagon, and attenuated GLP-1 responses during the OGTT, which is paralleled by lower estimates of insulin sensitivity and altered β-cell function." (PMID 38087928, 2024). "Similarly, propionate has been shown to increase glucose uptake, whereas butyrate did not; however, insulin signaling was improved by butyrate following palmitic acid (PA)-induced insulin resistance." (PMID 38398822, 2024). "However, while many EPCs have been shown to be epidemiologically correlated with the development of T2D and insulin resistance, there is no detailed mechanistic information on how these pollutants disrupt insulin metabolism." (PMID 39596044, 2024). "Though T2D is usually considered to be a disease of insulin resistance rather than insulin lack, for newly diagnosed patients, the origin may not be entirely clear or confined to a single pathobiologic cause." (PMID 39401034, 2024). "During OGTT, both fasting and stimulated insulin levels are within the normal range, although inadequately low for the respective glucose levels, and there are no clinical features of severe insulin resistance such as acanthosis nigricans." (PMID 39408828, 2024). "Therefore, modulation of insulin sensitivity through the opposing actions of AgRP activation and POMC inhibition may converge in the liver to counteract the development of systemic insulin resistance." (PMID 38378998, 2024). "As insulin also plays a pivotal role in the development of metabolic and reproductive disorders in dairy cattle, further research about catch-up growth, body composition in SGA-born heifers, and blood insulin levels to determine the presence of insulin resistance and metabolic function is warranted." (PMID 39123682, 2024). "Furthermore, limited by the data collection, the metformin dosage in patients with insulin resistance and post-treatment insulin levels were not available." (PMID 38807145, 2024). "Insulin resistance (IR) describes a situation wherein insulin fails to exert its effects on tissues, which is most commonly documented by a decrease/failure of tissue glucose uptake in the presence of insulin." (PMID 38473112, 2024). "This specificity can be also observed under high insulin concentrations, where protein synthesis is stimulated but has a minimal effect on glucose transporter proteins, leading to reduced insulin sensitivity rather than generalized insulin resistance." (PMID 39749015, 2024). "This aligns with prior research identifying SIRD as the most genetically unique subgroup, exhibiting an insulin resistance molecular signature and lacking associations with the type 2 diabetes locus in the TCF7L2 gene or insulin secretion risk scores, contrary to SIDD and MOD." (PMID 38625583, 2024). "While type 1 diabetes is characterized by a whole or near-total absence of insulin, type 2 DM encompasses a wide range of illnesses distinguished by reduced insulin production, different degrees of insulin resistance, increased glucose production, and modified fat metabolism." (PMID 39483582, 2024).
Insulin resistance (continued). "Therefore, the insulin resistance consensus group did not recommend the use of fasting insulin to screen for insulin resistance, and further research is needed to identify a strong surrogate marker of insulin resistance." (PMID 39523406, 2024). "Nevertheless, a number of subsequent investigations suggested that insulin and a high-fat diet may also induce the expression of betatrophin, leading to elevated serum TG and insulin resistance rather than enhanced glucose metabolism." (PMID 39030467, 2024). "Despite this we, couldn’t investigate the presence of insulin resistance, as fasting insulin levels being not available in this population for calculation of HOMA index." (PMID 38505744, 2024). "Current instruments employed for assessing insulin resistance in both epidemiological studies and clinical practice include the homeostasis model assessment of insulin resistance (HOMA-IR), HOMA of percentage beta-cell function (HOMA-β), and quantitative insulin sensitivity test index (QUICKI)." (PMID 40302954, 2024). "However, no significant changes were observed in insulin and insulin resistance indices, HbA1c, total cholesterol, HDL-c, LDL-c, CK, and other inflammatory indicators." (PMID 39029066, 2024). "A genetic deficiency of IL-1 or TNF receptors was reported to suppress the development of insulin resistance in diet-induced obesity mouse models, and in healthy participants, intravenous infusion of TNF-α was reported to decrease whole-body glucose uptake in insulin clamp tests." (PMID 38347961, 2024). "Modulating insulin signaling pathways through agents that enhance IRS-1 and IRS-2 function or inhibit their aberrant phosphorylation could improve glucose uptake and reduce insulin resistance." (PMID 39519193, 2024). "Although HOMA-IR, derived from blood glucose and insulin levels, has served as a reliable indicator for evaluating insulin resistance in numerous population-based studies, it may not capture the full complexity of the phenomenon." (PMID 38615017, 2024). "It has been explained in various literature that insulin plays a key role in triglyceride, LDL, and free fatty acid metabolism and there is enough evidence suggesting that diabetic dyslipidemia correlates strongly with hyperglycemia and hyperinsulinemia due to insulin resistance in T2D patients." (PMID 39583396, 2024). "Thus, they should not be construed as being definitive measures of insulin resistance and insulin sensitivity in our study." (PMID 37914981, 2024). "However, in the present study, no significant changes were observed in factors such as insulin and insulin resistance index in different groups." (PMID 38681576, 2024). "Notably, one study reported a negative relationship between marrow fat content and both fasting insulin levels and insulin resistance in premenopausal women, regardless of their obesity status." (PMID 39926390, 2024). "Fetuin-A is thought to contribute to insulin resistance through multiple mechanisms, including impairment of insulin receptor signaling, inhibition of GLUT-4 translocation, and reduction in PPARγ and adiponectin expression, as shown in obese insulin-resistant mice." (PMID 39409124, 2024). "Likewise, no appreciable changes were observed in insulin sensitivity measured directly by an insulin tolerance test or indirectly by assessment of the homeostasis model assessment index of insulin resistance (HOMA-IR)." (PMID 38713514, 2024). "In a study involving nondiabetic volunteers with obesity and insulin resistance, the supplementation of standardized poplar propolis extract powder for a period of three months positively affected insulin homeostasis through its impact on both insulin resistance and secretion." (PMID 38474354, 2024). "Insulin resistance in CGL individuals might be related to AGPATs role in the biosynthesis of PtdIns, the substrate for PI3K (phosphatidylinositol-3-kinase), which acts on membrane integrity and provides substrates for insulin signaling." (PMID 38755198, 2024).